HOXB7 (homeobox B7)
Diseases named in the same sentence as HOXB7 in open-access papers (continued):
Sharing a sentence is not in itself a finding about the gene and the disease.
tumor (continued). "Our results revealed that HOXB7 promotes ICC proliferation only in vivo, which may be caused by angiogenesis, one of the earliest processes involved in tumor growth and progression." (PMID 30664713, 2019). "HOXB7 expression was positively correlated with tumor progression and lung metastasis in vivo." (PMID 28454092, 2017). "A xenograft tumor model was established in nude mice to assess the role of HOXB7 in tumor growth." (PMID 28646927, 2017). "The role of HOXB7 in promoting tumor growth and metastasis was verified in vivo." (PMID 28646927, 2017). "Tumor weights were significantly lower in the HOXB7 shRNA group than in the control group (0.775±0.330 g vs. 4.475±0.126 g, P<0.001) and the formation of lung metastatic lesions was markedly decreased in the HOXB7 shRNA group (2.750±0.957 vs. 21.500±4.123, P<0.001)." (PMID 28454092, 2017). "Moreover, the patients with positive HOXB7 staining had shorter survival time and poorer prognosis across all tumor stages." (PMID 27901487, 2017). "We demonstrated that HOXB7 enhances proliferation, migration, and invasion of HCC cells through bFGF-induced MAPK/ERK pathway activation, and its expression was strongly associated with tumor recurrence and poor prognosis of HCC patients after surgery." (PMID 28454092, 2017). "In cohort I, high expression of HOXB7 protein was observed in 124 of 177 (70.1%) tumor samples." (PMID 26076456, 2015). "However, the over-expression of HOXB7 can markedly promote the transformation, proliferation, and survival of tumor cells." (PMID 25183455, 2014). "Next, we analyzed the expression of these genes using qRT-PCR in 50 pairs of NSCLC tissues (randomly selected according to each proportion of TNM stage in all the 192 patients) compared with the corresponding non-tumor tissues, and found that HOXB7 was upregulated in NSCLC tissues." (PMID 24853421, 2014). "The result--that HoxB7 and bFGF are expressed in HSA--may suggest that HoxB7 induces the proliferation of tumor cells mediated by bFGF." (PMID 19825192, 2009). "Moreover, the silence of HOXB7 reduced the tumor ball formation ability of HNSCC cells." (PMID 34303375, 2021). "In addition to the gross observations of differences in tumor volume, IHC staining showed that tumors formed by HOXB7-overpressing cells have stronger HOXB7 staining than tumors formed by control cells, which indicated the successful establishment of our xenograft tumor model." (PMID 30664713, 2019). "Moreover, the role of HOXB7 in promoting tumor growth and metastasis was verified in vivo." (PMID 30664713, 2019). "Moreover, the expression level of HOXB7 varied in the HCC tumor tissues." (PMID 28646927, 2017). "The roles of HOXB7 in enhancing the proliferation of tumor cells, as well as promoting migration and invasion functions of cancer cells during hematogenous dissemination, are presumably responsible for the high recurrence rate and poor prognosis observed in HOXB7-positive HCC patients." (PMID 28454092, 2017). "Furthermore, from a therapeutic viewpoint our data indicate that molecular therapies targeting HOXB7 in HCC might be a promising approach to blocking tumor progression." (PMID 28454092, 2017). "It has been found that HOXB7 could promote tumor cell proliferation in other solid tumors." (PMID 26076456, 2015). "The miRNA miR-337 may repress tumor cell proliferation and metastasis by targeting HOXB7." (PMID 25183455, 2014). "Increased gene expression of HOXB7, KIF2C, NEK2, FOXM1 and IGF2BP3 has also been reported for several other types of cancer, suggesting that these genes may be associated with tumor growth in general." (PMID 22879911, 2012). "Consistent with the previous results, HOXB7 and HOXC6 showed significantly higher expression in tumor tissues as compared to the adjacent normal tissues." (PMID 39980564, 2025). "NAT10, CCT3, PLEK2, HOXB7, FOXD1, SEC61G, and so on have been identified as tumor markers in HNSCC by performing TCGA HNSCC database analysis." (PMID 37679666, 2023).
tumor (continued). "⋄ TUG1 regulated genes: In NSCLC tumor tissues, TUG1 has been described to trans-downregulate the expression of Homeobox B7 (HOXB7), CELF1, and EZH2 (PRC2 subunit)." (PMID 32438606, 2020). "We then examined the expression of HOXB7 in post‐operative tumor tissues of patients with ESCC undergoing neoadjuvant chemotherapy, and the relationship between HOXB7 expression with TRG (tumor regression grade) and overall survival was analyzed." (PMID 31568655, 2020). "In this study, we comprehensively analyzed the expression and clinical significance of HOXB7 in HCC and explored its potential mechanism in tumor progression." (PMID 28454092, 2017). "We found HOXB7 was highly expressed in HCC cell lines with highly metastatic potential and cancerous tissues from patients with tumor recurrence." (PMID 28454092, 2017). "This study comprehensively analyzed the expression and clinical significance of HOXB7 in HCC and explored its potential mechanism in tumor progression." (PMID 28454092, 2017). "Besides, we also evaluated the expression differences of HOXB7 and HOXC6 between tumor tissues and normal tissues in LUAD (based on log2(FPKM+1)), and both exhibit greater expression in tumor tissues with significant differences (p<0.001)." (PMID 39980564, 2025). "HOXB7 can be targeted indirectly via MEK/ERK inhibition or more directly through HOX/PBX interaction inhibitors such as HXR9, which has shown preclinical anti-tumor efficacy in other HOX-driven cancers." (PMID 41040515, 2025). "Therefore, the outcomes of these experiments in vitro showed that HOXB7 and HOXC6 are key oncogenes that promote tumor malignant behavior and cell proliferation in LUAD cell lines." (PMID 39980564, 2025). "Recently, the panel of tumor suppressor miRNAs in the context of OSCC has been expanded to include miR-5580-3p and miR-376c-3p, which target Laminin Subunit Gamma 2 (LAMC2) and Homeobox B7 (HOXB7), respectively." (PMID 41209683, 2025). "Moreover, HOXB7 knockdown significantly inhibited cell proliferation, migration and invasion and induced cell apoptosis in HNSCC cells, and resulted in compromised tumour growth in vivo." (PMID 34303375, 2021). "Additionally, Western blot analysis of HOXB7 protein revealed that over-expression of MAGI2-AS3 suppressed its expression and conversely, MAGI2-AS3 silencing enhanced the expression in mouse tumor tissues (p < 0.05)." (PMID 33330444, 2020). "Although the biological functions of HOXB7 in various cancers have been described, its function in the controlling tumorigenesis and tumor progression of ICC has not been well characterized." (PMID 30664713, 2019). "Due to the heterogeneity between different samples, HOXB7 expression varied in both tumor and non-tumor tissues." (PMID 30664713, 2019). "Comparative analysis indicated that expression of HOXB7 was significantly increased in GC tumor tissue relative to adjacent noncancerous gastric tissues (P<0.05)." (PMID 27901487, 2017). "Expression of HOXB7 was analyzed by qPCR in 36 GC patients' tissues, in both tumor and paired adjacent noncancerous regions of the tissues." (PMID 27901487, 2017). "As the top one significantly changed pathways after HOXB7 siRNA treatment, MAPK pathway might be an important one in the regulation of tumor progression by HOXB7." (PMID 28454092, 2017). "Implantation of the HOXB7-overexpressing cell line MGC-803-B7 resulted in significantly faster tumor growth than in the MGC-803-NC group, and the tumor volumes for MGC-803-B7 (930.53 ± 129.20 mm3) were significantly larger than the MGC-803-NC control (186.31 ± 103.82 mm3) (t-test, P<0.05)." (PMID 27901487, 2017). "In univariate analysis, alpha-fetoprotein (AFP) level, gamma-glutamyl transpeptidase (GGT) level, tumor size, tumor number, vascular invasion, tumor encapsulation, satellite lesion, BCLC stage, and HOXB7 expression were unfavorable predictors for OS and/or TTR (except tumor size)." (PMID 28454092, 2017).
tumor (continued). "Comparative analysis indicated that HOXB7 was significantly upregulated in 23 examined tumor samples (18/23) compared with adjacent noncancerous tissues (9/23) (P = 0.039)." (PMID 26076456, 2015). "Since RA was previously shown to upregulate HOXB7 expression, and upregulation could be suppressed by THAL, we tested the expression of this gene in tumours excised at the end of the 18-day treatment period." (PMID 26362268, 2015). "In addition, IHC was used to detect the expression of HOXB7 protien in NSCLC and corresponding non-tumor lung tissues." (PMID 24853421, 2014). "In contrast, all of the corresponding non-tumor lung tissues showed negative or weakly positive immunostaining of HOXB7 protein." (PMID 24853421, 2014). "Therefore, HOXB7 may drive distinct migratory properties and promote cell fate plasticity by activating EMT, thus facilitating metastasis and tumor recurrence in BC." (PMID 41040515, 2025). "Moreover, western-blot analysis in tumor tissues revealed that patients with tumor recurrence exhibited higher HOXB7 protein expression than those without recurrence (P<0.001)." (PMID 28454092, 2017). "Thus, modulation of tumor proliferation and invasiveness through inhibiting the activation of AKT or MAPKs (ERK and p38α) mediated by HOXB7 expression may be a promising therapeutic target for GC prevention and therapy." (PMID 27901487, 2017). "On the other hand, treatment of the human GBM cell line U343 with RA induced expression of different genes (HOXB7, FGF2, VEGF, and IL-8) that may contribute to tumour cell proliferation, hypoxia, and angiogenesis, thereby potentially limiting the therapeutic efficacy of RA." (PMID 26362268, 2015). "Surprisingly we did not observe induction of HOXB7 in tumours treated with RA." (PMID 26362268, 2015). "Second, our primary focus was to elucidate HOXB7’s biological functions and H-Ras/ERK–mediated mechanisms; although the tumor immune microenvironment was not examined, it remains an important future direction to clarify whether HOXB7-driven ERK activation contributes to immune modulation." (PMID 41040515, 2025). "While this was not completely aligned with a non-significant increase S/G2/M phases of AD-MSC-HOXB7, it could be that HOXB7 may play a different role in primary MSC compared to the tumor cell lines where it acts as oncogene dramatically increasing cell proliferation." (PMID 30890185, 2019).
cancer (56 papers, 2011 to 2026). A tumor composed of atypical neoplastic, often pleomorphic cells that invade other tissues. "The downregulation of HOXA5 increased the expression of HOXB6 and HOXB7, which were associated with poor clinical outcomes in cancer patients." (PMID 35054365, 2022). "Our newly coverage together with previous findings above point out that not only HOXB7 serves as a novel diagnostic and prognostic cancer biomarker, but also shows tremendous potential as a therapeutic target." (PMID 34303375, 2021). "HOXB7 is commonly believed to be dysregulated in several types of cancers and associated with cancer progression." (PMID 30664713, 2019). "It is generally recognized that HOXB7 is dysregulated in several types of cancers and associated with cancer progression." (PMID 28646927, 2017). "Increased expression of HOXB7 has been reported in several malignancies and has been implicated in influencing a number of cellular processes, including cell invasion, DNA repair, metastasis, and angiogenesis, and is thought to contribute to tumorigenesis and poor survival in many cancers." (PMID 27901487, 2017). "Many HOX genes, especially HOXB7 and HOXC6, have higher expression and lower overall survival in specific cancers and are predicted as risk factors." (PMID 39980564, 2025). "HOXB7 and HOXC6 were positively correlated with TMB in most cancers, and HOXB7 was strongly correlated with TMB in ACC, HNSC, PAAD, and STAD, and HOXC6 was strongly correlated with TMB in COAD, LGG, MESO, and PRAD (R>0.2)." (PMID 39980564, 2025). "Among the HOX gene family, Homeobox B7 (HOXB7) has been identified as a key player in multiple types of cancer, including genitourinary tumors." (PMID 41040515, 2025). "Since the HOXB7 gene is also related to migratory pathways, cancer cell migration was assessed after treatment with HNP-siHOXB7 by the scratch assay in the MCF7 cell line." (PMID 39458966, 2024). "Studies have shown that the HOXB gene cluster contributes to cancer development; increased expression of HOXB3, HOXB6, HOXB7, HOXB8, and HOXB9 in LUAD patients is linked with poor overall survival (OS)." (PMID 36506331, 2022). "The regulation of two critical members of MAPK pathways (ERK, p38α) by HOXB7 at their phosphorylation level contributes to the enhanced migratory and invasive properties of cancer cells." (PMID 34617205, 2022). "Further, microarray data of 394 HCC tissues confirmed that HOXB7 modulates the biological functions of cancer cells via the activation of the MAPK/ERK pathway." (PMID 34617205, 2022). "To unveil the molecular basis behind these aggressive and often untreatable cancers, here we explored the contribution of HOXB7 deregulation for their aggressiveness." (PMID 34680970, 2021). "A report showed that the homeobox gene HOXB7 promotes F-actin polymerization and migration in cancer cells." (PMID 33535170, 2021). "Firstly, we used publicly available sets such as TCGA (The Cancer Genome Atlas) and GEO (Gene Expression Omnibus) datasets to analyze relevant information on HOXB7 expression patterns." (PMID 34303375, 2021). "As a direct target of HOXB7 emerging cancer gene and pluripotency factor LIN28B was identified that sustained the expansion of a subpopulation of cells with stem cell characteristics." (PMID 32830458, 2021). "HOXB7 (Homeobox protein Hox-B7) is a transcription factor, whose amplifying is closely related to cancer cell proliferation and survival." (PMID 34298612, 2021). "The homeobox gene Homeobox B7 (HOXB7) is overexpressed across a range of cancers and promotes tumorigenesis through varying effects on proliferation, survival, migration and invasion." (PMID 34303375, 2021). "Changes in the expression of HOXB7 also affected the proliferation, apoptosis and radio-resistance of cancer cells." (PMID 33330444, 2020).
cancer (continued). "As it has been reported HOXB7 can regulate the invasion and migration of cancer cells, we examined the effects of HOXB7 overexpression on the invasion and migration abilities of ICC cells." (PMID 30664713, 2019). "IL8 has been regarded as an important factor regulating cancer metastasis and we also observed that HOXB7 altered IL8 expression." (PMID 30664713, 2019). "HOXB7 has been reported to promote cancer cell proliferation, but other researchers have stated that this protein is not involved in proliferation." (PMID 30664713, 2019). "HOXB7 is involved in many of the major cellular processes that occur in cancer, including proliferation, invasion, migration, angiogenesis and the epithelial–mesenchymal transition (EMT)." (PMID 30664713, 2019). "Homeobox B7 (HOXB7) protein is reported to be aberrantly expressed in a variety of cancers and to play an important role in multiple cellular processes." (PMID 30664713, 2019). "Its overexpression in these cancer cells suppressed fission, proliferation, migration and invasion and induced cell apoptosis via targeting the transcription factor HOXB7." (PMID 30301470, 2018). "As an important transcription factor, HOXB7 regulates many cancer cell functions, including proliferation, invasion, migration, angiogenesis and epithelial-mesenchymal transition (EMT)." (PMID 28646927, 2017). "Although many studies have shown that HOXB7 plays an important role in cancer development, the biological functions of HOXB7 in GC tumorigenesis, progression and prognosis have not been well characterized." (PMID 27901487, 2017). "HOXB7 is a member of the homeobox gene family and has been shown to play an important role in various cancer-related processes, including proliferation, metastasis, and angiogenesis." (PMID 28646927, 2017). "Overexpression of HOXB7 is correlated with poor prognosis of patients with many different cancers, such as esophageal squamous cell carcinoma, colorectal cancer and oral cancer." (PMID 27901487, 2017). "In GC patients, increased expression of HOXB7 was observed in cancer tissue compared with adjacent normal tissues." (PMID 27901487, 2017). "Studies have shown that in these cancers, HOXB7 overexpression promotes cell proliferation, DNA repair, angiogenesis, epithelial mesenchymal transition (EMT) and cell survival." (PMID 27901487, 2017). "As a member of class I homeobox genes, the transcription factor homeobox B7 (HOXB7) is known to play an important role in tumorigenesis in several cancers, including melanoma, breast, lung, colorectal and pancreatic cancers." (PMID 27901487, 2017). "The expression of HOXB7 in cancer tissues was classified as high (score ≥6) in 181 cases (45.9%) and low (score 0-5) in 213 cases (54.1%), whereas there were almost no cases of high HOXB7 expression in adjacent non-cancerous tissues (data not shown)." (PMID 28454092, 2017). "Several studies have demonstrated that the progression of several types of cancer is regulated by HOXB7 via AKT, ERK, TGF-β, Ras/Rho and VEGF." (PMID 28646927, 2017). "Although many genes have been shown to be directly or indirectly regulated by HOXB7 in other cancer cells, only a few of them have been identified as direct targets, including bFGF." (PMID 26076456, 2015). "It has been shown that overexpression of HOXB7 is involved in the differentiation, proliferation, and invasion of many cancer cells in vitro." (PMID 25183455, 2014). "In accordance, the reduced number of animals with micro-metastasis in HNP-siHOXB7 and cotreatment groups (20%) could be due to reduced cancer cell migration as HOXB7 depletion reduced migratory potential of MCF7 cells in vitro." (PMID 39458966, 2024). "Among these, HOXB7, HOXA13, HOXA10, and HOXC10 have been associated with cancer." (PMID 38761291, 2024). "In addition, homeobox (HOX) genes such as HOXB7, HOXC8, and HOXB13, which are used as PC diagnostic markers, are involved in malignant cell transformation and/or cancer progression." (PMID 36428807, 2022).